FOXP3 (forkhead box P3)
Diseases named in the same sentence as FOXP3 in open-access papers (continued):
Sharing a sentence is not in itself a finding about the gene and the disease.
psoriasis (continued). "Notably, two additional forkhead box family members (FOXM1 and FOXP3) are also ranked within the top 30 regulators in psoriasis." (PMID 35874668, 2022). "Furthermore, a group of IL-17A+/Foxp3+/CD4+ triple-positive cells were identified in the lesional skin of psoriasis patients." (PMID 34975883, 2021). "In these studies, it was reported that miR-210 regulated Treg cell functions by targeting FOXP3 in psoriasis and increased levels of miR-210 in psoriasis could skew T cells differentiation to Th17 and Th1, but not to Th2." (PMID 33356031, 2021). "The expression of microRNA-210 is increased in circulating CD4+ T cells from patients with psoriasis, and this increase may contribute to the reduced Foxp3 mRNA and protein levels in the patients’ CD4+ T cells." (PMID 34501328, 2021). "The reduced levels of vitamin D3 and/or VDR may be related to defects in Tregs in psoriasis via the reduction of Foxp3 expression." (PMID 34501328, 2021). "In a study of patients with psoriasis, it is found that IL-21 up-regulates RORγt expression and down-regulates the expression of Foxp3, increases secretion of IL-17A and IL-22, and finally induces T-helper 17 (Th17) and Tregs imbalance and promotes inflammation in psoriasis." (PMID 34490267, 2021). "CD4+Foxp3+ Treg cells are involved in the pathogenesis of psoriasis." (PMID 34768720, 2021). "Our evidence suggests that MDSCs may induce the conversion of T effector cells to T regulatory cells in psoriasis patients, indicating that FOXP3+ Treg populations are a potential biomarker for the distinction between these two psoriatic TCM syndrome groups." (PMID 32382290, 2020). "Our data revealed that IL-21 could downregulate Foxp3 expression, which is a critical transcription factor in Treg cells, suggesting a role of IL-21 in the impaired function of Treg cells in psoriasis patients." (PMID 31440249, 2019). "Given that esculetin induced CD4+Foxp3+ Tregs in IMQ-induced psoriasis-like mice, we further asked whether the effects of esculetin on skin lesion of the psoriatic mice were dependent on CD4+Foxp3+ Tregs." (PMID 30258447, 2018). "Therefore, we quantified CD4+ Foxp3+ Tregs in spleens and lymph nodes of psoriasis-like mice in vivo and determined the effects of PSORI-CM02 on CD4+ CD25+ Treg proliferation in vitro." (PMID 29358932, 2017). "Further, we verified significant levels of FOXP3 in psoriasis lesions from severe patients." (PMID 28042206, 2016). "Foxp3+Treg in peripheral blood mononuclear cells (PBMCs) tended to be lower in psoriasis patients (Treg/CD4; 4.57±2.40%) than in healthy volunteers (Treg/CD4; 6.00±1.39%) before bath-PUVA therapy, but increased significantly after bath-PUVA therapy in all patients (Treg/CD4; 6.40±2.85%)." (PMID 23365685, 2013). "Interestingly, abnormal FOXP3 gene expression and regulatory T-cell dysfunction also may play a role in the pathogenesis of psoriasis and psoriatic arthritis." (PMID 39744276, 2024). "The Foxp3-3279 AC and IVS9+459 GG genotypes were associated with an increased risk of psoriasis in a Chinese population, indicating that they may increase the risk for psoriasis by quantitatively and functionally influencing Tregs." (PMID 34501328, 2021). "In addition, CD4+CD25+Foxp3+ Tregs could differentiate into IL-17A–producing Th17 cells in psoriasis and aggravate its symptoms by inducing imbalance of Th17/Treg, activating effecting T cells and immune response in skin." (PMID 33981308, 2021). "Besides autoreactive T-lymphocytes, Tregs are also thought to contribute to psoriasis through ineffective control of proinflammatory cells: while CD4+CD25+FOXP3+ cells are readily detectable in the blood of psoriasis patients, they are unable to suppress Th1 effects." (PMID 31191553, 2019). "Thus, we evaluated whether esculetin would alleviate psoriasis through inducing CD4+Foxp3+ Tregs in vivo." (PMID 30258447, 2018).
psoriasis (continued). "Based on the data from the in vitro studies, the possible mechanisms underlying the improvement in psoriasis caused by MSC exosomes may involve inhibiting T cell proliferation, inhibiting Th1 and Th17 differentiation, and inducing Treg by influencing FOXP3 expression." (PMID 41007656, 2025). "on skin tissue from a patient with psoriasis and vitiligo comorbidity revealed elevated levels of CD4, CD8, Foxp3, and IL‐17A in the comorbid skin tissue." (PMID 39031921, 2024). "The results of studies suggest that resistin plays an important role in the development of psoriasis by affecting inflammatory factors such as TNF-α and reducing the population of Foxp3+ Treg cells." (PMID 36675592, 2023). "Taken together, AOA can reduce the production of Th17-mediated inflammatory factors and increase Foxp3+ Tregs by inhibiting both activated serine metabolism and mTOR in the skin of a TPA-induced psoriasis mouse model." (PMID 37649889, 2023). "Consistent with previous studies, we found that Foxp3 and CD25 were negatively expressed in CD8αα+T cells of patients with psoriasis, and unexpectedly, CD122 was also expressed little." (PMID 35663772, 2021). "PV patients presented distinct Th17/Treg immune imbalance and highly expressed Notch1 and Hes-1 mRNA levels, which were positively correlated with psoriasis area and severity index (PASI) and the ratios of Th17/Treg and RORγt/Foxp3." (PMID 29686529, 2018). "Our results demonstrated that PSORI-CM02 upregulated the frequency of CD4+ Foxp3+ Tregs in vivo and promoted in vitro proliferation of CD4+ CD25+ Tregs as well, indicating that these Tregs play a role in attenuation of murine psoriasis by PSORI-CM02." (PMID 29358932, 2017). "Bath-PUVA therapy also improved Psoriasis Area and Severity Index (PASI) scores and increased Foxp3+ Treg in all patients." (PMID 23365685, 2013). "Our results suggest that the high expression of GZBM, GBP5 and FOXP3 in CD8+ T cells drives the pathogenesis of psoriasis, therefore, inhibiting the expression of GZBM, GBP5 and FOXP3 is expected to be a new strategy to alleviate the progression of psoriasis." (PMID 38915827, 2024). "Accordingly, forkhead box p3 (Foxp3)-negative Treg-of-B cells were recently shown to promote M2 macrophage polarization through STAT6 activation in an imiquimod-induced psoriasis model." (PMID 38791342, 2024). "Effect of bath-PUVA therapy was reported on three distinct Foxp3+ subsets: activated Tregs (aTregs), resting Tregs (rTregs), and cytokine-secreting non-suppressive T-cells from peripheral blood of psoriasis patients and healthy controls." (PMID 36901778, 2023). "Alterations in FOXP3 (rs3761548; G>C/T/A) can potentiate the inflammatory cascade in psoriasis and consequently not respond to and/or provoke AEs due to MTX treatment." (PMID 37761008, 2023). "In conclusion, our findings suggested that Foxp3− Treg‐of‐B cells could induce alternatively activated M2 macrophages through STAT6 activation, providing a cell‐based therapeutic strategy for psoriasis." (PMID 37073709, 2023). "In addition, during sepsis, adenosine promotes the expression of Foxp3 in Treg cells through JNK/AP-1 pathway, while JNK-phospho-c-JUN (ser63/73) pathway plays an important role in Foxp3 nuclear translocation in psoriasis." (PMID 36389828, 2022). "microRNA-210 binds to the 3′-untranslated region of Foxp3, and the overexpression of microRNA-210 inhibits Foxp3 expression in CD4+ T cells from healthy controls, whereas inhibition of microRNA-210 increases Foxp3 expression in CD4+ T cells from patients with psoriasis." (PMID 34501328, 2021). "In our study, we found that the number of CD4+ CD25+ FoxP3+ Treg cells was also not altered in psoriasis patients, but we did not conduct in-depth research on Treg cells." (PMID 35186952, 2021).
psoriasis (continued). "In the IMQ induced psoriasis-like mice, (R)-Salbutamol administration reduced the expression of IL-17 in plasma along with a downregulation of the CD4+ Th17+ T cells (Th17) and upregulation of the CD3+CD4+ T cells and CD25+ Foxp3+ Tregs in the spleens." (PMID 32102363, 2020). "In patients with psoriasis, TGFβ-1 induces the generation of FOXP3 positive Treg cells in the absence of IL-6 and the production of Th-17 cells in the presence of IL-6." (PMID 30744173, 2019). "Interestingly, depleting CD4+Foxp3+ Tregs largely reversed esculetin-mediated reduction in PASI scores, indicating that esculetin attenuates murine psoriasis mainly by inducing CD4+Foxp3+ Tregs." (PMID 30258447, 2018). "Soler and McCormick (2011) demonstrated that psoriasis patients really had regulatory T cells presenting FOXP3, although most of them were nonfunctional." (PMID 28042206, 2016). "As far as we researched, there is no articles relating genetic polymorphism of FOXP3 and TNBC susceptibility in a Brazilian population, but positive associations have been proposed with other diseases such as psoriasis and allergic rhinitis." (PMID 24877082, 2014). "This suggests that the role of miR-4296 in the pathogenesis of psoriasis may be via other relevant target genes rather than directly through the inhibition of FOXP3." (PMID 33356031, 2021). "We have found that two other drugs (calcitriol and paclitaxel) that indeed reduce inflammation in psoriasis, however, may not be very effective in psoriasis treatment because they inhibit PPARγ or FOXP3." (PMID 34445309, 2021). "We hypothesize that the expression of IL17, STAT3, FOXP3, and RORC and FOSL1 genes in psoriatic skin is correlated with the level of PPARγ expression, and they belong to the same signaling pathway that regulates the development of psoriasis lesion." (PMID 33133175, 2020). "As IL-21 expression was markedly increased in psoriasis patients and could promote CD4+ T cell proliferation and Th17 cell differentiation and also inhibited the expression of Foxp3, we then measured the proportion of Th17 and Treg cells in the PBMCs of psoriasis patients." (PMID 31440249, 2019). "In a mouse model of psoriasis (K5.hTGF-b1 transgenic mice), 4-week PUVA treatment suppressed the IL-23/Th17 pathway while augmenting the frequencies of Th2 and IL-10 secreting Foxp3 + Treg, in a CTLA-4 dependent manner, and the levels of many inflammatory cytokines were reduced." (PMID 31533744, 2019). "At this stage, it is unclear whether the altered FOXP3 isoform ratio in psoriasis depends on activated non-Treg cells or impaired Treg cells." (PMID 29593749, 2018). "Also, it was highlighted that in psoriasis there is up-regulation of Th17 and down-regulation of regulatory T cells (Treg), which is evidenced by up-regulation of retinoic-acid-receptor-related orphan nuclear receptor gamma (ROR-ɤ) and down-regulation of fork head box P3 (FOXP-3)." (PMID 37010718, 2023). "Draining lymph node and spleen cells were isolated from IMQ-induced psoriasis-like mice 7 days after treatment without or with esculetin, and CD4+Foxp3+ Tregs were detected via flow cytometric analysis." (PMID 30258447, 2018). "A well designed study proved that inhibition of PKCα pathway using Sorastaurin can stabilize Treg phenotype as evidenced by maintenance of high Foxp3 and CD25 expression, and lack of IL-17A and IFNγ production and has shown efficacy in clinical trials of psoriasis." (PMID 26652024, 2015).
pancreatic cancer (91 papers, 2008 to 2025). "Spatial transcriptomics of primary pancreatic cancer revealed cellular heterogeneity and an enrichment of FOXP3-associated Tregs in the tumor front, suggesting that the immunosuppressive microenvironment promotes metastatic dissemination." (PMID 40806346, 2025). "FOXP3+ regulatory T cells (Tregs) have been found to be associated with survival in patients with pancreatic cancer in existing studies." (PMID 37284203, 2023). "The pooled hazard ratios (HRs) with 95% confidence intervals (95% CI) were used to evaluate the association between FoxP3+Treg cells and survival outcomes of pancreatic cancer patients." (PMID 34654443, 2021). "We found that 41.3% of pancreatic cancer patients had PD-L1-positive staining; both PD-L1 expression levels and FOXP3+ Treg infiltration were significantly associated with depth of invasion, lymph node metastasis, distant metastasis, and pTNM." (PMID 33062072, 2020). "In a previous study, FOXP3+ Treg infiltration was reportedly associated with poor prognosis in pancreatic cancer patients." (PMID 33062072, 2020). "We analyzed the clinical and pathological aspects associated with the accumulation of FOXP3+ lymphocytes in pancreatic cancer." (PMID 25191901, 2014). "Moreover, lower protein expression of Foxp3 was significantly associated with higher severity of cachexia in patients with pancreatic cancer." (PMID 34900737, 2021). "These pooled results showed that a high density of tumor-infiltrating FoxP3+Treg cells are associated with poor survival and high recurrence, regardless of whether they are found in the intratumoral or peritumoral tissue of pancreatic cancer." (PMID 34654443, 2021). "Importantly, our study demonstrated a new association between the density of FOXP3+ lymphocytes in pancreatic cancer and lymph node metastasis." (PMID 25191901, 2014). "The median density of FOXP3+ lymphocytes (4/HP) in each tumor was considered to be the cutoff level and was analyzed in comparison to the patients' age, gender, histological grade and T stage of the tumor to identify the risk factors of lymph node metastasis in pancreatic cancer." (PMID 25191901, 2014). "Immunofluorescence staining revealed that CD4 FOXP3 cell numbers in PT tissues from patients with late-stage pancreatic cancer were significantly higher than those in patients with early-stage pancreatic cancer." (PMID 40303346, 2025). "The included studies showed a significant correlation between high expression of TLS and FOXP3 in pancreatic cancer patients." (PMID 39259184, 2024). "As a result, inhibiting the AKT1/FOXP3/CERS6 axis can be a possible tactic to prevent the growth of pancreatic tumors." (PMID 38919615, 2024). "Foxp3 also confers a suppressive phenotype on Tregs in pancreatic cancer cells by repressing the transcriptional activation of several T cell-stimulated target genes, such as Interleukin-2 (IL-2)." (PMID 38919615, 2024). "A meta‐analysis identified prognostic factors for tumor infiltrating lymphocytes in pancreatic cancer, and CD8 was found to be associated with good OS while FOXP3 was associated with poor prognosis." (PMID 36650632, 2023). "Further CD4/FOXP3 immunofluorescence co-staining confirmed the higher levels of infiltration of Treg cells in pancreatic cancer tissue." (PMID 37753069, 2023). "During the immunohistochemical, we found the infiltration of FoxP3+ T cells is at a low level in pancreatic cancer." (PMID 36835933, 2023). "In line with this, murine pancreatic cancer cells reportedly converted naïve T cells to CD4+FOXP3+ Treg cells by releasing TGFβ." (PMID 38038865, 2023). "In pancreatic ductal adenocarcinoma, the FoxP3 expression was demonstrated in pancreatic cancer cells with tumor-infiltrating Tregs through the FoxP3/C-C motif chemokine ligand 5 (CCL5)/C-C motif chemokine receptor 5 (CCR5) pathway." (PMID 37569676, 2023).
pancreatic cancer (continued). "In the majority of tumor types, the localization of FoxP3 expression is predominantly nuclear, besides the cytoplasmatic expression in pancreatic cancer." (PMID 36980787, 2023). "TGF-β is a potent inducer of Foxp3 expression in Tregs and has also been reported to control Foxp3 expression in pancreatic carcinoma cells." (PMID 37766222, 2023). "Previous studies have revealed that peripheral CD4+FOXP3+ Tregs and MDSCs decreased after gemcitabine-based chemotherapy in patients with pancreatic cancer." (PMID 36333670, 2022). "A previous study revealed that pancreatic cancer cells expressing high FOXP3 levels promoted the level of Treg infiltration through the secretion of TGF-h." (PMID 35174076, 2022). "The aim of our meta-analysis was to determine the impact of FoxP3+Treg cells on the survival of pancreatic cancer patients." (PMID 34654443, 2021). "Accordingly, FoxP3+Treg cells can be considered as a promising therapeutic target in pancreatic cancer." (PMID 34654443, 2021). "Most studies in pancreatic cancer suggest that high levels of FoxP3+Treg cells are a poor prognostic factor, but there are also reports of no predictive value." (PMID 34654443, 2021). "We identified studies reporting the prognostic value of FoxP3+Treg cells in patients with pancreatic cancer." (PMID 34654443, 2021). "Correlation analyses revealed a strong positive correlation between SOCS1 and Foxp3 in the cachectic pancreatic cancer patients." (PMID 34900737, 2021). "The pooled HR is 1.70 (95% CI 1.04 ~ 2.78; P< 0.05) which indicated that FoxP3+ T level was also correlated with the recurrence of pancreatic cancer." (PMID 34654443, 2021). "We pooled OS and recurrence indicators (DFS/PFS/RFS) to assess the impact of intratumoral FoxP3+ T levels on the prognosis of pancreatic cancer." (PMID 34654443, 2021). "In contrast, pancreatic cancer exhibited more aggressive growth and excessive peritoneal seeding as well as a decreased ratio of cytotoxic T cells to FoxP3 + Treg cells after splenectomy." (PMID 33129308, 2020). "Correlations among PD-L1 expression levels, FOXP3+ Treg infiltration, and clinicopathological characteristics of pancreatic cancer patients were investigated." (PMID 33062072, 2020). "They found that FOXP3, a master transcription factor of Tregs, is also expressed in pancreatic cancer cells (named as cancer-FOXP3, or c-FOXP3) and transactivated CCL-5 to recruit FOXP3+Tregs to mediate immune evasion." (PMID 32594906, 2020). "On the other hand, the gut microbiome from a short-term survivor of pancreatic cancer promoted pancreatic tumor growth in a mouse model via increasing the infiltration of CD4+FOXP3+ and myeloid-derived suppressor cells." (PMID 32962112, 2020). "In the present study, PD-L1 expression levels and FOXP3+ Treg infiltration were evaluated in a cohort of 63 patients with pancreatic cancer." (PMID 33062072, 2020). "FOXP3+ Treg infiltration in pancreatic cancer patients was evaluated and negatively correlated with prognosis." (PMID 33062072, 2020). "In conclusion, our study showed that PD-L1 and FOXP3 are prognostic biomarkers for pancreatic cancer." (PMID 33062072, 2020). "PD-L1 expression levels and FOXP3+ Treg infiltration are correlated with prognosis of patients with pancreatic cancer." (PMID 33062072, 2020). "In the present study, the PD-L1 expression levels and the FOXP3+ Treg infiltration were investigated in a cohort consisting of 63 pancreatic cancer patients." (PMID 33062072, 2020). "The PD-L1 expression and FOXP3+ Treg infiltration were measured in 63 pancreatic cancer samples using immunohistochemistry." (PMID 33062072, 2020). "Remarkably, in vivo depletion of Gr-1+ cells in tumor-bearing mice led to a significant reduction in Treg cells (CD4+Foxp3+) in the pancreatic tumors." (PMID 32038621, 2019). "In summary, our findings show that the systemic depletion of MDSCs inhibits the recruitment and/or induction of Foxp3+ Tregs in pancreatic tumors." (PMID 32038621, 2019).